GSTM5 (glutathione S-transferase mu 5)
Description:
Conjugation of reduced glutathione to a wide number of exogenous and endogenous hydrophobic electrophiles.
Synonyms: GSTM5-5; GTM5
Tractability: PROTAC: ubiquitination databases record sites on it; its protein half-life has been measured.
Target class: Enzyme; Transferase
Gene: Protein-coding gene on chromosome 1 (109,711,746 to 109,775,428, forward strand). Ensembl gene ENSG00000134201.
Subcellular location: Cytoplasm
Subcellular location (Human Protein Atlas): Cytosol; Cytokinetic bridge; Microtubules; Primary cilium; Primary cilium tip; Primary cilium transition zone
Pathways (Reactome):
Metabolism: Glutathione conjugation
Gene Ontology:
Molecular function: glutathione transferase activity; identical protein binding; protein binding
Biological process: glutathione metabolic process
Cellular component: cytosol; cytoplasm
Genetic constraint (gnomAD): Loss-of-function variants: 21 observed, 28.34 expected, observed/expected ratio (o/e) 0.74, 90% interval 0.52 to 1.07. The upper end of that interval is the gene's LOEUF score, 1.07, which puts it in group 4 of 6, group 1 being the genes least tolerant of losing a copy. Missense variants: 269 observed, 251.76 expected, observed/expected ratio (o/e) 1.07, 90% interval 0.97 to 1.18. Synonymous variants: 82 observed, 90.78 expected, observed/expected ratio (o/e) 0.9, 90% interval 0.75 to 1.09.
Homologues: Orthologues: chimpanzee GSTM5 (98% identical), rabbit GSTM2 (78% identical), tropical clawed frog gstp1 (31% identical), Caenorhabditis elegans gst-16 (24% identical), Caenorhabditis elegans gst-35 (24% identical), zebrafish gstp1.1 (24% identical), Caenorhabditis elegans gst-14 (23% identical), Caenorhabditis elegans gst-37 (23% identical), Caenorhabditis elegans gst-1 (23% identical), Caenorhabditis elegans gst-10 (23% identical), Caenorhabditis elegans gst-23 (23% identical), Caenorhabditis elegans gst-34 (23% identical), and 31 more. Paralogues in human: GSTM1 (88% identical), GSTM4 (83% identical), GSTM2 (80% identical), GSTM3 (72% identical), GSTP1 (28% identical), GSTA2 (24% identical), GSTA1 (23% identical), GSTA3 (23% identical), GSTA5 (22% identical), HPGDS (22% identical), GSTA4 (22% identical).
Diseases named in the same sentence as GSTM5 in open-access papers:
GSTM5 is named in the same sentence as 53 diseases in open-access papers, as found by Europe PMC text mining. Sharing a sentence is not in itself a finding about the gene and the disease. The quoted sentences say what the papers report.
bladder cancer (8 papers, 2016 to 2026). "For instance, in bladder cancer, GSTM5 overexpression has been linked to reduced cell proliferation, migration, and colony formation, while in lung adenocarcinoma, aberrant GSTM5 expression correlates with poor overall survival." (PMID 40868127, 2025). "GSTM5, an antioxidant gene, has been implicated in the progression of solid tumors such as colorectal cancer, bladder cancer, and lung adenocarcinoma." (PMID 38236327, 2024). "GSTM5, as a part of the GST family, has been associated with various cancer types, including breast cancer, prostate cancer, ovarian cancer, bladder cancer, and colorectal cancer." (PMID 41523912, 2026). "Research has revealed that GSTM5 is upregulated in tumors such as Barrett’s adenocarcinoma, lung adenocarcinoma, bladder cancer, prostate cancer, and breast cancer." (PMID 38236327, 2024). "Methylation of the GSTM5 promoter region has also been reported in several malignant tumors, including bladder cancer, Barrett's adenocarcinoma and thyroid carcinoma." (PMID 35729618, 2022). "When comparing 50 patients with 50 healthy subjects, GSTM5 DNA methylation level was significantly higher in bladder cancer tissues than in healthy urine pellets." (PMID 33802702, 2021). "The levels of GSTM5 gene expression and DNA methylation were analyzed in patients with bladder cancer, and functional studies of GSTM5 were conducted using GSTM5 overexpression in cultured bladder cancer cells." (PMID 33802702, 2021). "The present study revealed that low GSTM5 gene expression and high GSTM5 DNA methylation level tended to bladder cancer and that patients with bladder cancer and high GSTM5 expression had a longer relapse-free survival." (PMID 33802702, 2021). "In our previous study, GSTM5 mRNA expression was enhanced in 5637 bladder cancer cells following treatment with 10 μM 5-aza-dC; the DNA CpG methylation level of the GSTM5 promoter was also decreased from 84.6 to 61.5%." (PMID 33802702, 2021). "In our previous study, the GSTM5 gene was found to be heavily CpG methylated and expressed at low levels in human bladder cancer cells." (PMID 33802702, 2021). "Our previous study demonstrated that the glutathione S-transferase Mu 5 (GSTM5) gene is highly CpG-methylated in bladder cancer cells and that demethylation by 5-aza-dC activates GSTM5 gene expression." (PMID 33802702, 2021). "In the present study, the DNA methylation level of human GSTM5 was analyzed in patients with bladder cancer and normal subjects, and GSTM5 was overexpressed in bladder cancer cells to assess changes in cancer-associated characteristics." (PMID 33802702, 2021). "Clinical analysis revealed that the GSTM5 mRNA expression was lower in bladder cancer tissues than in normal tissues and that the level of GSTM5 DNA methylation was higher in bladder cancer tissues than in normal urine pellets." (PMID 33802702, 2021). "The GSTM5 mRNA expression data of patients with bladder cancer were extracted from the publicly available Oncomine database." (PMID 33802702, 2021). "Because the GSTM5 gene all existed in 7 bladder cancer cell lines and SV-HUC-1 cells, the expression and regulation of GSTM5 was also analyzed in other cell lines." (PMID 27404495, 2016). "Similarly, in bladder cancer, GSTM5 acts as a tumor suppressor, and its promoter hypermethylation results in decreased expression, reduced glutathione levels, and enhanced tumor progression." (PMID 40868127, 2025). "In addition, GSTM5 is expressed at low levels in human bladder cancer cells and tumor cell growth is inhibited when GSTM5 is overexpressed." (PMID 38474004, 2024). "The aim of the present study was to investigate the role of GSTM5 in bladder cancer." (PMID 33802702, 2021). "In these three databases, GSTM5 mRNA was downregulated in superficial and infiltrating bladder tumor tissues compared with normal tissues, suggesting that GSTM5 may play a tumor suppressor role in human bladder cancer." (PMID 33802702, 2021).
bladder cancer (continued). "In summary, down-regulation of the GSTM1 gene and the p21 protein might act as biomarkers in nitrosamines-induced bladder carcinogenesis in mice, while GSTM1 null and GSTM5 hypermethylation might act as bladder cancer biomarkers in humans." (PMID 27404495, 2016). "As high GSTM5 expression was associated with a higher probability of relapse-free survival, in the future, increasing GSTM5 expression may be a consideration for bladder cancer therapy, and GSTM5 DNA methylation level may be a useful biomarker for patients with bladder cancer." (PMID 33802702, 2021). "In view of the inhibited gene activation and expression of GSTM5 caused by DNA CpG methylation, the DNA methylation level of GSTM5 was analyzed using tumors from patients with bladder cancer and urine pellets from healthy individuals with no previous history of bladder cancer." (PMID 33802702, 2021). "In the present study, the GSTM5-reduced GSH level inhibited the proliferation of bladder cancer cells but did not affect sensitivity to cisplatin and mitomycin C." (PMID 33802702, 2021). "In summary, GSTM5 plays a tumor suppressor role in bladder cancer cells without significantly affecting chemoresistance to cisplatin and mitomycin C, and the cellular GSH levels highlight a key mechanism underlying the cancer inhibition effect of GSTM5." (PMID 33802702, 2021).
lung cancer (6 papers, 2016 to 2024). A malignant neoplasm involving the lung. "The GST family is closely related to the occurrence and development of many tumors, and the same GSTM5 as a member is abnormally expressed in ovarian cancer and nonsmall cell lung cancer." (PMID 36685007, 2023). "The methylation status of GSTM5 in the promoter region in lung cancer cells was measured by methylation-specific PCR (MSP)." (PMID 35729618, 2022). "After 5-aza-2'-deoxycytidine treatment of lung cancer cells, expression of GSTM5, cell proliferation and migration were assessed by RT-PCR, CCK-8 and transwell assays, respectively." (PMID 35729618, 2022). "In vitro studies, our study indicated that the promoter region of GSTM5 was methylated in A549 lung cancer cells and GSTM5 gene expression was related to the promoter region methylation status." (PMID 35729618, 2022). "Then, we investigated the effects of 5-Aza-CdR on the methylation level and the expression of GSTM5 in lung cancer cell line." (PMID 35729618, 2022). "A decrease in GSTM5 was also observed in the sporadic lung cancer-prone genomic instability mouse model Sgo1−/+." (PMID 34070461, 2021). "The results showed that the GSTM5 gene methylation was reversed by 5-Aza-CdR, and the methylation inhibitor could restore the gene expression in lung cancer cells." (PMID 35729618, 2022). "Moreover, methylation-specific PCR also showed that the GSTM5 gene promoter was hypermethylated in lung cancer cells, and treatment with 5-Aza-CdR can restore the gene expression and inhibit cell proliferation and migration." (PMID 35729618, 2022). "Furthermore, the relationship between the methylation status of GSTM5 promoter and the gene expression in lung cancer cells was investigated." (PMID 35729618, 2022). "Genes associated with cell immune functions were enriched in these pathways, such as COPS5, GSTM5, and TPI1, indicating the critical role of 5hmC modifications in immune response in lung cancer treatment." (PMID 38667328, 2024). "For instance, PCSK9 (6.3-fold increase), CEL (15.1-fold increase), or GSTM5 (3.9-fold decrease), despite their relatively important deregulation, had only been reported in lung cancer for PCSK9, pancreatic and nasopharyngeal carcinoma for CEL, Barret esophagus and glioblastoma for GSTM5." (PMID 28962550, 2017). "In addition to GSTM5, human GSTM2 has been found to be silenced by promoter hypermethylation in lung cancer cells, and GSTM2, 3 and 5 promoter hypermethylation was also found in Barrett’s adenocarcinoma." (PMID 27404495, 2016).
prostate carcinoma (6 papers, 2021 to 2026). A carcinoma that arises from epithelial cells of the prostate gland. "For example, the gene expression of GSTM5 is lower in tumor tissues than in normal tissues in Barrett’s adenocarcinoma, GSTM5 expression is downregulated in breast and prostate cancer." (PMID 33802702, 2021). "Furthermore, low expression levels of GSTM5 were also observed in breast cancer, prostate cancer and Barrett's adenocarcinoma." (PMID 35729618, 2022). "Finally, three pathway genes (GSTP1, GSTM5, RRM2) with non-zero coefficients were obtained for constructing the prostate cancer prediction model." (PMID 40426879, 2025).
Barrett adenocarcinoma (5 papers, 2013 to 2024). An adenocarcinoma arising from Barrett metaplastic epithelium in the esophagus. "GSTM5 has also been found to be dysregulated in a variety of tumors, such as Barrett's adenocarcinoma, low-stage non-small cell lung cancer, ovarian carcinoma." (PMID 35729618, 2022). "A study of Barrett’s adenocarcinoma indicated that the gene expression of GSTM2, GSTM3 and GSTM5, but not GSTM4, was lower in tumors than in normal tissues and that DNA methylation also regulates gene expression." (PMID 33802702, 2021).
colorectal cancer (5 papers, 2022 to 2026). A primary or metastatic malignant neoplasm that affects the colon or rectum. "The survival analysis indicated dysregulated GSTM5 expression in colorectal cancer samples was associated with poor survival." (PMID 35729618, 2022). "In colorectal cancer, the expression of Gstm5 was reinforced by miR-20b-3p and actively regulates miR-20b-3p/GSTM5/AKT-mTOR signaling axis." (PMID 36671013, 2023).
Hypertension (5 papers, 2012 to 2025). The presence of chronic increased pressure in the systemic arterial system. "SNP rs11807 in the 3′ region of GSTM5 was found to be associated with hypertension." (PMID 23181071, 2012). "The proteomic response that contributes to the SHR phenotype and reduction of hypertension in Taichong-needled rats includes the modulation of seven proteins related to oxidative stress, including SOD, ALDH2, GSTM5, GLUD1, protein DJ-1, HSP90α, and α-ETF." (PMID 22984478, 2012). "In our previous study, the proteomic response that contributes to the SHR phenotype and reduction of hypertension in LR3-needled rats includes the modulation of seven proteins related to oxidative stress in the medulla oblongata, including SOD, ALDH2, GSTM5, GLUD1, protein DJ-1, Hsp90a, and a-ETF." (PMID 29853959, 2018).
ovarian carcinoma (5 papers, 2023 to 2026). A malignant neoplasm originating from the surface ovarian epithelium. "In ovarian cancer, GSTM5 expression has been associated with stemness features and therapeutic response." (PMID 40868127, 2025). "A study on ovarian cancer reported decreased GSTM5 expression in cancer tissue compared to normal tissue, and the expression was positively correlated with ovarian cancer prognosis." (PMID 39519120, 2024). "It has been reported that Gstm5 expression was significantly downregulated in ovarian cancer and lung adenocarcinoma." (PMID 36671013, 2023). "Although direct evidence in PC is still limited, the genetic and molecular similarities between prostate, breast, and ovarian cancers support further exploration of redox and epigenetic therapies in PC, particularly in molecularly defined subgroups with GSTM5 dysregulation." (PMID 40868127, 2025). "Notably, treatment with investigational anticancer agents such as AICAR, an AMPK activator, and PI-103, a dual PI3K/mTOR inhibitor, was shown to restore GSTM5 expression and increase treatment sensitivity in resistant ovarian cancer cells." (PMID 40868127, 2025).
breast carcinoma (4 papers, 2022 to 2026). "In breast cancer, GSTM5 downregulation via promoter methylation has been linked to increased cell proliferation and migration." (PMID 40868127, 2025).
lung adenocarcinoma (4 papers, 2022 to 2025). A carcinoma that arises from the lung and is characterized by the presence of malignant glandular epithelial cells. "In lung adenocarcinoma, GSTM5 promoter hypermethylation has also been identified as a key gene-silencing mechanism, correlating with poor prognosis and reduced survival." (PMID 40868127, 2025).
gastric cancer (2 papers, 2022 to 2024). A primary or metastatic malignant neoplasm involving the stomach. "The GSTM5 expression is associated with macrophage and mast cell activation and positively correlated with prognosis in lung, ovarian, and gastric cancer." (PMID 38667328, 2024).
steatosis (2 papers, 2013 to 2018). Increased lipid within the cytoplasm of cells. "Several studies reported that GSTM1, GSTM2, GSTM4 and GSTM5 mRNA levels are suppressed in patients with steatosis and NASH." (PMID 30080863, 2018). "GSTM2, GSTM4, and GSTM5 mRNA levels are expressed at lower levels in patients with steatosis and NASH." (PMID 23346097, 2013).
anemia (1 paper, 2025). A reduction in the number of red blood cells, the amount of hemoglobin, and/or the volume of packed red blood cells. "Gstm5 is associated with refractory anemia with excess blast progression." (PMID 40574855, 2025).
Bladder Urothelial Carcinoma (1 paper, 2022). "For example, the editing level on two ubiquitination sites, chr1:110256304 on GSTM5 and chr4:10080600 on WDR1, were significantly different between tumor and para-tumor samples in Bladder Urothelial Carcinoma (BLCA) and Head and Neck squamous cell carcinoma (HNSC), respectively." (PMID 36064557, 2022).
brain tumors (1 paper, 2013). "Aberrant DNA hypermethylation and downregulation of GSTM5 have also been reported in brain tumors, salivary gland cancers and leukemia." (PMID 23818951, 2013).
colon cancer (1 paper, 2022). "However, it has also been reported that GSTM5 was up-expressed in colon cancer tissues than in corresponding normal tissue." (PMID 35729618, 2022).
depression (1 paper, 2024). "Moreover, overexpression of GSTM5 protein was found to be significant in a rat model of depression." (PMID 39727940, 2024).
eosinophilia (1 paper, 2015). "The promoter region of GSTM5 was hypermethylated in patients with anticipated and known clonal eosinophilia." (PMID 26497854, 2015).
Infertility (1 paper, 2017). "Of the proteins we identified, ATP5O, PHGPX, SOD2, and GSTM5 showed significant connections to several diseases, including neoplasia, carcinoma, infertility, and others known to be related to oxidative damage, lipid peroxidation, and apoptosis." (PMID 27384531, 2017). "We found that four proteins (PHGPX, GSTM5, SOD2, and ATP5O) were potentially linked to infertility, neoplasia, carcinoma, and other disorders, perhaps as a consequence of oxidative stress, lipid peroxidation, apoptosis, cell proliferation, ionic homeostasis, or a combination of these processes." (PMID 27384531, 2017).
leiomyoma (1 paper, 2013). A well-circumscribed benign smooth muscle neoplasm characterized by the presence of spindle cells with cigar-shaped nuclei, interlacing fascicles, and a whorled pattern. "The methylation levels of the GSTM5 promoter in leiomyomas were higher than those in myometrium while mRNA levels of GSTM5 in leiomyomas were remarkably lower than those in myometrium in all the 10 samples." (PMID 23818951, 2013). "The genes associated with “cancer process” contained potentially novel or relevant candidate genes for leiomyoma formation such as IRS1, COL4A1, COL4A2, COL6A3, and GSTM5." (PMID 23818951, 2013).
liver cancer (1 paper, 2023). An epithelial or non-epithelial malignant neoplasm that arises from the liver. "In addition, LINC00907 (logFC = −2.6057), CCN1 (logFC = −2.05925), GSTZ1 (logFC = −2.34197), and GSTM5 (logFC = −2.8954) were lowly expressed in liver cancer tissues." (PMID 36685007, 2023).
major depression (1 paper, 2024). "Nevertheless, some other relevant overexpressed genes detected after CASh analysis of the major depression datasets include EXOSC2 (Exosome Component 2), DPP10 (Dipeptidyl Peptidase Like 10), GSTM5 (Glutathione S-Transferase Mu 5), and ZNF184 (Zinc Finger Protein 184)." (PMID 39727940, 2024).
male infertility (1 paper, 2019). The inability of the male to effect fertilization of an ovum after a specified period of unprotected intercourse. "We found that GSTM5 and VDAC2, which were higher in LFS, were involved with spermatogenesis, the acrosome reaction, and male infertility." (PMID 31488871, 2019).
meningioma (1 paper, 2016). A generally slow growing tumor attached to the dura mater. "In a combined cytogenetic and expression study, GSTM5 was among those genes that were downregulated in meningiomas with complex karyotypes." (PMID 27096627, 2016).
ovarian serous cystadenocarcinoma (1 paper, 2021). A malignant serous cystic epithelial neoplasm arising from the ovary. "GSTM5 expression was also shown to be a positive biomarker for survival in ovarian serous cystadenocarcinoma." (PMID 33802702, 2021).
Parkinson disease (1 paper, 2018). A progressive degenerative disorder of the central nervous system characterized by loss of dopamine producing neurons in the substantia nigra and the presence of Lewy bodies in the substantia nigra and locus coeruleus. "For example,the rs11807 in the GSTM5 gene was shown association withdiagnosis age of Parkinson disease." (PMID 30108424, 2018).
trisomy 21 (1 paper, 2025). A chromosomal disorder consisting of the presence of an extra chromosome 21. "Similarly, SERPINA5 and PLG mediate coagulation and fibrinolysis, while GSTM5 participates in oxidative stress defense—mechanisms often disturbed in chromosomal abnormalities and reported in trisomy 21 placentas." (PMID 41614738, 2025).